CTLA4 (cytotoxic T-lymphocyte associated protein 4)
Diseases named in the same sentence as CTLA4 in open-access papers (continued):
Sharing a sentence is not in itself a finding about the gene and the disease.
melanoma (continued). "Furthermore, patients with advanced melanoma exhibited decreased circulating MDSCs and increased intratumoral CD8+ T cells following neoadjuvant anti-CTLA-4 treatment." (PMID 32111080, 2020). "In our studies, B cell depletion does not influence the growth of B78 melanoma tumors, the tumor response to RT + IT-IC + anti-CTLA-4, or the immunologic memory established by this treatment." (PMID 32849544, 2020). "B cell depletion did not affect either the growth rate of untreated B78 melanoma or the response of these tumors to RT + IT-IC + anti-CTLA-4." (PMID 32849544, 2020). "Moreover, combined anti-CTLA-4+anti-PD-1 therapy has enhanced efficacy that exceeded either of the anti-CTLA-4 and anti-PD-1 monotherapies in melanoma patients." (PMID 33149194, 2020). "The anti-CTLA4 antibody has variable response among different syngeneic models with marked response in CT26, GL261, and EMT6, while it was shown to be ineffective in B16F10, a melanoma model." (PMID 31898484, 2020). "This will be performed on a larger cohort of advanced melanoma patients treated with anti-PD-1 in combination or not with anti-CTLA-4, from a prospective clinical trial (IMMUSPHINX: NCT03627026) we are currently conducting in our institute." (PMID 31974367, 2020). "In contrast with this immunologically ‘cold’ B78 melanoma model, tumors in control mice treated only with α-CTLA-4 continued to grow and no CRs were observed (n=8)." (PMID 32690669, 2020). "These indications prompted the application of CTLA-4 blockade in patients with stage III/IV unresectable melanoma with remarkable success, culminating in the 2011 FDA approval of the anti-CTLA-4 monoclonal antibody (mAb), ipilimumab, as an adjuvant therapy for patients with cutaneous melanoma." (PMID 32283684, 2020). "Median OS was 7.5 months for concomitant CTLA-4-inhibitors, 17.8 months for concomitant BRAF-inhibitors and 20.4 months for concomitant anti-PD-1 treatment in a retrospective study of 108 melanoma patients receiving SRT for brain metastases (notably, 40% of patients received an additional WBRT)." (PMID 32487100, 2020). "Furthermore, dual ICB, which targets both PD-1 and CTLA-4 at the same time, has shown greater efficacy than single ICB in patients with metastatic NSCLC and melanoma, and is more effective in melanoma patients with smaller baseline tumor diameters." (PMID 33597954, 2020). "Another study found that EZH2 inactivation reversed the resistance to anti-CTLA-4 and IL-2 immunotherapy and suppressed melanoma growth in a consequence of accumulating IFN γ, producing PD-1 low CD8+ T cells and PD-L1 downregulation on melanoma cells." (PMID 32708698, 2020). "Therefore, we have explored the predictive performance of kinase activity profiling in PBMCs from advanced melanoma and NSCLC patients treated with anti-PD-1 or anti-CTLA-4 monotherapy." (PMID 33427690, 2020). "Gene expression data from pre-treatment melanoma samples revealed immune-related signatures that were highly expressed in patients whose tumors responded to anti-CTLA4 or anti-PD-1 therapy, compared to non-responders." (PMID 32133005, 2020). "In melanoma patients treated with anti-PD-1, anti-CTLA-4 or the combination, myeloid cells were enriched in non-responder lesions." (PMID 32793228, 2020). "For example, PEG-PLA NPs [poly(ethylene glycol)-block-poly(D,L-lactide)] loaded with CTLA-4 siRNA efficiently restored the T-cell functions by downregulating CTLA-4 level and increasing the CD4+ and CD8+ T cell populations as well as inhibited tumor growth in mice with melanoma (Li S.-Y." (PMID 33409265, 2020). "Together with targeted therapy for BRAF mutated patients, the backbone of treatment in advanced melanoma is represented by the immune therapy with either anti-CTLA4 or anti-PD1 agents, that remove immune checkpoint inhibition to potentiate the immune response to melanoma." (PMID 33193402, 2020).
melanoma (continued). "The efficacy of CTLA-4 inhibition in melanoma bearing mice was significantly reduced in mice lacking either ICOS or its ligand." (PMID 32970735, 2020). "The melanoma scRNA-seq dataset consists of 48 FACS-sorted CD45+ samples (i.e., all the immune cells were sorted) from 32 patients with metastatic melanoma before and after either anti-PD-1, anti-CTLA-4, or combination treatment." (PMID 33065980, 2020). "Major (> 50%) or complete loss of MHC-I expression on membranes of melanoma cell was associated with transcriptional repression of HLA-A, HLA-B, HLA-C, and B2M in 78/181 patients (43%), which could predict the resistance to anti-CTLA-4 antibody therapy but not anti-PD-1 therapy." (PMID 32864131, 2020). "This study demonstrates that combination therapy with anti-CTLA-4 and anti-PD-1 antibodies does not affect myeloid-driven vascular and systemic inflammation in melanoma patients and hyperlipidemic mice." (PMID 34396271, 2020). "Conversely, although performed in a limited number of patients, our results did not demonstrate a significant increase in sPD-L1 levels in melanoma treated with either anti-PD-1 or CTLA-4 mAbs (data not shown)." (PMID 32033266, 2020). "Interestingly, in an analysis of eight pooled cohorts including baseline samples from 190 patients with unresectable melanoma, elevated PD-L1 expression on peripheral blood CD4+ and CD8+ T cells predicted resistance to CTLA-4 blockade." (PMID 31775882, 2019). "Combination therapy of the CTLA-4 antibody, ipilimumab, and radiation therapy was also well-tolerated and effective in patients with stage IV melanoma without any unexpected toxicities." (PMID 31533363, 2019). "In this study, CTLA-4 blocking therapy was found to be effective against sarcoma, melanoma, and colon cancer in SPF mice but not in GF mice." (PMID 32010123, 2019). "In contrast, PD-L1, PD-L2, and CTLA-4 expression did not correlate to anti-PD-1-responsiveness of melanoma patients." (PMID 31555274, 2019). "Studies in melanoma and lung cancer mouse models suggest that NK responses could be mediated through the CD28/CTLA-4:B7–1/B7–2 system, by direct inhibition of NK IFN-γ production." (PMID 31395100, 2019). "Therefore, genomic changes in tumors from 68 patients with advanced melanomas, who progressed on anti-CTLA-4 treatment or were anti-CTLA-4 therapy-naïve, before and after anti-PD-1 initiation were determined." (PMID 31557787, 2019). "Two very recent clinical trials in drug-treatment naïve patients with melanoma BrM [ABC trial and CheckMate 204 trial] reported a 46 and 52% intracranial response rate respectively following combined anti-PD-1 plus anti-CTLA-4 therapy." (PMID 31824260, 2019). "PD-1/PD-L1 combined with CTLA-4 is currently one of the most commonly used immunological checkpoint combinations, and has been approved by the FDA for use in advanced renal carcinoma and melanoma." (PMID 31014381, 2019). "Whether anti-CTLA4 ICB induces or, alternatively, reveals an immune-resistant state in a subset of melanomas is an important question that deserves further evaluation." (PMID 31792460, 2019). "Specifically, about 60–80% of the melanoma patients do not response to initial PD-1/CTLA-4 antibody therapy (primary resistance), and 20–30% of the initial responders develop resistance to treatment, with progressive disease." (PMID 31110180, 2019). "A systematic review and meta-analysis, for example, has shown distinct patterns of irAEs according to the ICI class (CTLA-4 or PD-1/PD-L1) or tumor type (melanoma or non-melanoma)." (PMID 31575933, 2019). "The introduction of checkpoint inhibitor therapy has revolutionized the adjuvant therapy of melanoma; however, there remains a role for IFN-α in this setting based on the potential for cancer immune escape or autoimmune events with CTLA-4 and PD-1 blocking antibodies." (PMID 30725205, 2019).
melanoma (continued). "While inhibitors to CTLA-4 and the PD-1/PD-L1 axis are well-established for the clinical management of melanoma, many patients do not respond or develop resistance to these interventions." (PMID 30941125, 2019). "Interestingly, these findings are nicely in line with recent observations by Gide and colleagues showing that differentiated effector memory T cells are more abundant in melanoma patients who respond to PD1 and CTLA-4 antibody treatment." (PMID 31176366, 2019). "Melanoma cells frequently evade the immune system by overexpressing negative immune checkpoints e.g. CTLA-4." (PMID 31554169, 2019). "Using the solid B16-OVA melanoma tumor model, we have previously demonstrated a synergy between MS–OVA (enc) and CPI therapy (anti-PD-1, anti-programmed death-ligand 1 (anti-PD-L1) and anti-CTLA-4) in promoting long-term tumor-free survival in C57BL/6 mice." (PMID 31771150, 2019). "In contrast, the combinations of CTLA4/PD-1 checkpoint inhibitors in renal cancer and melanoma show no more activity than that predicted by the independent contributions of the monotherapies." (PMID 30374524, 2019). "CTLA-4 is one of the immunosuppressive molecules and its expression is reported to be upregulated in chronic infections and tumors, such as HIV, HCV, esophageal cancer, and melanoma." (PMID 31665022, 2019). "Recent studies have similarly demonstrated that the anti-CTLA-4 mAb does not reduce Tregs in bladder cancer, prostate cancer, nor melanoma." (PMID 31134084, 2019). "Ipilimumab, the anti- cytotoxic T lymphocyte antigen 4 (anti-CTLA-4) antibody, was FDA-approved in 2015 for the adjuvant treatment of resected stage III melanoma, though it is infrequently used in the adjuvant setting due to its unfavorable side effect profile." (PMID 29773080, 2018). "Emerging evidence indicates that existing immune checkpoint inhibitors, such as anti-PD-1, anti-PD-L1, and anti-CTLA4 antibodies, can be effective monotherapies for immune-sensitive cancers, including NSCLC and malignant melanoma, but they lack efficacy in the case of pancreatic cancers." (PMID 29996538, 2018). "Mice lacking CD4 T cells were unresponsive to CTLA-4 antibody treatment when challenged with a transplantable melanoma cell line." (PMID 29032503, 2018). "Since landmark publications have shown the significant clinical efficacy of PD-1 and/or CTLA-4 blockade in patients with melanoma and other non-treatable cancers, much attention has been drawn to immune checkpoint receptors and their cognate ligands." (PMID 30250471, 2018). "Another research study published recently also drew a correlation between CD45RO+CD8+ memory T cells and clinical response to anti-CTLA-4 therapy, but not anti-PD-1 therapy in melanoma patients." (PMID 29510697, 2018). "Evidence from clinical trials suggests the positive correlation between high tumor mutational loads and improved clinical efficacy of ICB-based therapies (including anti-PD-1, anti-PD-L1, and anti-CTLA-4) in NSCLC and melanoma, which have the highest mutation burdens as well as response rates." (PMID 30294272, 2018). "CTLA-4 (CD152) was the first immunoregulatory molecule to be targeted for therapeutic purposes utilizing the humanized antibody Ipilimumab approved by FDA and EMA in 2011, initially for melanoma, soon followed by Tremelimumab for mesothelioma." (PMID 30406030, 2018). "The results of our experiment demonstrated that while RIT was quite effective in reducing the melanoma nodules in the lungs of the mice, no reduction was observed in anti-CTLA4 mAb group." (PMID 29615812, 2018). "Taken together, the CD4+ T-cell compartment of young melanoma patients, but not old melanoma patients, shows increased expression of the checkpoint inhibitor PD-1 but not CTLA-4." (PMID 29546435, 2018). "In contrast, we observed no clear modulation of CTLA-4 in CD4+ T cells of melanoma patients and healthy controls." (PMID 29546435, 2018).
melanoma (continued). "More recently, a head-to-head comparison of the anti-PD-1 mAb, Nivolumab, and the anti-CTLA-4 mAb, Ipilimumab, as adjuvant therapy for resected stage III and IV melanoma showed that Ipilimumab had a lower CITE but higher irAE,13 further dimming the prospect of CTLA-4-targeting immunotherapy." (PMID 29463898, 2018). "Such evidence suggests that CTLA-4 treatment induces a CD8 T cell response against new targets in melanoma patients, rather than boosting a pre-existing immune response." (PMID 29032503, 2018). "A study of patients with melanoma brain metastases showed that concurrent immunotherapy with anti-PDL1 and anti-CTLA4 given within 4 weeks of stereotactic radiosurgery led to improved response of brain lesions relative to treatments that were separated by more than 4 weeks." (PMID 29556198, 2018). "We speculate that the KIR genotype may prove important for melanoma patients in different contexts, and that the KIR genotype may affect the outcome of anti-CTLA4 treatment or NK cell adoptive transfer therapies." (PMID 30374122, 2018). "A de novo expression of CTLA-4 was induced in 71.4% (5/7) and 85.7% (6/7) vs. 42.8% (3/7) IC-negative melanoma cells, treated with guadecitabine and DAC vs. AZA, respectively, with mean values ± SD of CTLA-4 molecules 1.16E-03 ± 1.73E-03 and 1.44E-03 ± 2.49E-03 vs. 2.31E-04 ± 1.07E-04, respectively." (PMID 30581389, 2018). "Several novel targeted therapeutic agents including immunotherapy drugs have been developed and approved for advanced melanoma treatment, including BRAF inhibitors (vemurafenib), anti-CTLA-4 agents (ipilimumab), and anti-PD-1 agents (nivolumab and pembrolizumab)." (PMID 30537980, 2018). "Metastatic melanoma patients that did not respond to CTLA-4 treatment were found to have tumours with genetic defects in IFNGR1/2, IRF1 and JAK2." (PMID 29875199, 2018). "Following in vitro studies that supported CTLA-4 as a key checkpoint molecule in the antitumor immune response, anti-CTLA-4 blocking antibody therapy was initially tested in numerous animal models including breast, prostate, lymphoma, colon and melanoma." (PMID 28866656, 2018). "Anti-CTLA4 antibody has been reported to prolong survival in progressive melanoma and was approved by the FDA as an immune checkpoint inhibitor against progressive melanoma in 2011." (PMID 29464025, 2018). "IRAEs are less frequent in anti-PD-1 treated patients than in those treated with CTLA-4 blockade (13.3% as opposed to 19.9% in anti-CTLA-4 treated patients) leading to approval of anti-PD-1 treatment as first line for advanced melanoma in the USA and the EU." (PMID 28866656, 2018). "We found that the inhibitory effect of CQ on the growth of B16 melanoma and H22 hepatocarcinoma was enhanced by IPI-549, along with further depression of T-cell PD1 and CTLA-4 expression, suggesting that PI3Kγ inhibition has a synergistic effect on CQ-triggered antitumor immunity." (PMID 29491374, 2018). "Percentages of PD-1 and CTLA-4 expressing CD8+ T cells were comparable in melanoma patients and healthy controls, irrespective of age." (PMID 29546435, 2018). "In melanoma patients, an improved clinical response rate was observed upon treatment with a combination of anti-CTLA-4/PD-1 with radiotherapy, compared to treatment without radiation." (PMID 29875199, 2018). "Additionally, DC-based immunotherapy combined with anti–CTLA-4 treatment has been shown to be more effective than the use of these agents alone in two small trials, showing a best ORR of 38% in melanoma patients." (PMID 30477198, 2018). "This approach has proven to be effective in the treatment of melanoma, but data supporting the effectiveness of anti-CTLA4 in the treatment of EC have not been reported so far." (PMID 29163851, 2017). "Presence of a transcriptional signature termed IPRES (innate anti-PD-1 resistance) in melanoma biopsy specimens was enriched for patients resistant to PD-1 inhibition but did not predict response to anti-CTLA-4 therapy." (PMID 28807052, 2017).
melanoma (continued). "PD-1 inhibitors and CTLA-4 inhibitors have been FDA approved for melanoma and non-small-cell lung cancer trials." (PMID 29263783, 2017). "In melanoma, several preliminary biomarkers have been investigated in response to ipilimumab (anti-CTLA-4) treatment, but none have been validated in subsequent studies." (PMID 28331613, 2017). "Triple combination of ISF35, anti-PD-1, and anti-CTLA-4 results in complete eradication of injected and noninjected subcutaneous tumors, as well as melanoma tumors in the brain." (PMID 29129918, 2017). "A large fraction of patients with cancer, including melanoma, do not experience tumor regression after single-checkpoint or dual-checkpoint blockade with anti-PD-1 and anti-CTLA-4 mAbs, likely due in part to insufficient spontaneous antitumor T cell immunity." (PMID 29129918, 2017). "Monotherapies involving the use of anti-CTLA-4 and PD-1 monoclonal antibodies have proven efficacy in the treatment of melanoma and non-immunogenic tumors such as non-small lung cell cancer and renal cell carcinoma." (PMID 29033936, 2017). "Although IS scores were validated in melanoma patients treated with anti-CTLA-4 antibodies, we cannot rule out the possibility that IS scores are more specific to tumor vaccines and probably to melanoma." (PMID 29051489, 2017). "We investigated whether melanoma and NSCLC sensitivity to PD-1 and CTLA-4 treatment was enhanced in tumours where tumours had a high clonal neoantigen burden." (PMID 28716075, 2017). "Expanded TILs were obtained from patients with advanced melanoma who had received Ipilimumab in the previous six months, or had not received any type of anti-CTLA-4 antibody." (PMID 28423678, 2017). "With the clinical success of targeting checkpoint inhibitors CTLA4 and PD1 in melanoma, there is a broadened interest in applying immunotherapy to a larger spectrum of malignancies (45 trials combining aPD1 and RT, 35 trials combing aCTLA4 and RT [clinicaltrials.gov on 5/2/2016])." (PMID 27281029, 2016). "CTLA-4 blockade was shown to potentiate the production of TAA-specific antibodies as well as a CD4+ and CD8+ antigen-specific T cell response in patients with melanoma, ovarian and prostate cancer." (PMID 26788324, 2016). "An important phase 3 trial of advanced melanoma patients showed that the CTLA-4 inhibitor ipilimumab significantly improved overall survival with or without co-administration of the melanoma antigen gp100." (PMID 27275004, 2016). "We observed this in a poorly immunogenic mouse model of human melanoma, which did not respond to α-PD-1 mAbs alone or in combination with α-CTLA-4 mAbs." (PMID 27160390, 2016). "CTLA-4 was the first immune checkpoint receptor targeted for cancer immunotherapy, and the anti-CTLA-4 antibody ipilimumab is used in the clinic for treatment of advanced melanoma." (PMID 26870040, 2016). "Ipilimumab (anti-CTLA-4) was approved in 2011, and pembrolizumab and nivolumab (anti-PD-1) were approved in 2014 by U.S. Food and Drug Administration (FDA) for the treatment of melanoma." (PMID 27917371, 2016). "In a phase I clinical trial on 16 patients with melanoma treated with the combination of MART-1 peptide-pulsed DCs and tremelimumab (anti-CTLA-4), a higher rate of durable objective tumor responses was observed than the rates expected with each agent administered alone." (PMID 27827885, 2016). "For example, melanoma patients with high PD-L1 expression did not respond to anti-CTLA4 mAb and radiation, implicating PD-1/PD-L1 signaling in this resistance (NCT01497808)." (PMID 31093342, 2016). "Therefore, α-CD137/α-PD-1 therapy outperformed the capacity α-CTLA-4/α-PD-1 or IL-2 treatment to synergize with SBRT in this mouse model, even though IL-2 in combination with SBRT-induced anti-tumor responses in human melanoma patients." (PMID 27160390, 2016).